CDKN1A (cyclin dependent kinase inhibitor 1A)
Diseases named in the same sentence as CDKN1A in open-access papers (continued):
Sharing a sentence is not in itself a finding about the gene and the disease.
tumor (continued). "For example, cyclin-dependent kinase inhibitor 1A (CDKN1A, also known as p21Cip1/Waf1), a tumour-suppressor downregulated in many cancers, is targeted by at least 28 miRNAs." (PMID 33800703, 2021). "Among the genes consistently altered in HT29, HCT116, and SW620 cells, 13 genes had previously been reported associated with tumor metastasis, such as BTG2, MXD1, CDKN1A, and HMGA2." (PMID 33791222, 2021). "The CDKN1A (p21) protein seems to perform contrasting tumor suppressor or oncogenic functions in neoplastic cells." (PMID 34833004, 2021). "The expressions of miR-520h and CDKN1A in tumor tissues of xenograft models, generated by subcutaneous injection of IGF2-AS stably over-expressed HepG2 were detected by qRT-PCR assay." (PMID 34516353, 2021). "Many studies have shown that TGF-β can serve as a tumour suppressors to induce the expression of Smad7 and p21(CDKN1A) in certain cancers." (PMID 31728016, 2020). "The pathways induced by these stimuli finally converge in a set of senescence genes, the best known of which are the tumor suppressors Cdkn2a-p16, Cdkn2a-p19, Cdkn1b-p27, Cdkn2b-p15 or Cdkn1a-p21, resulting in proliferative arrest." (PMID 32584785, 2020). "This is supported by the strong CDKN1A positivity seen in tumor cell nuclei of almost half of the analyzed chRCC." (PMID 32079343, 2020). "Nuclear staining with any intensity and a cutoff of ≥2% positive tumor cells proved to be the best criteria to differentiate between CDKN1A expression status and patient outcome." (PMID 32079343, 2020). "The expression of CDKN1A in tumor tissues was lower than that in adjacent non‐neoplastic tissues in over 90% (35/38) of patients." (PMID 33037696, 2020). "The expression of CDKN1A negatively correlated with the oncolytic effect of M1 in 44 tumor cell lines." (PMID 33037696, 2020). "CDKN1A is a tumor suppressor that mainly functions as a cell cycle checkpoint by binding to CDK1, Cyclin‐dependent kinase 2 (CDK2), or the CDK4/6 complex." (PMID 33037696, 2020). "The expression of CDKN1A in tumor tissues was lower than that in adjacent non‐neoplastic tissues in 58% (83/143) of patients." (PMID 33037696, 2020). "We have observed a significant correlation between CN loss, decreased CDKN1A expression and poor prognosis, suggesting a tumor suppressive role of CDKN1A in chRCC." (PMID 32079343, 2020). "Oral gastric nutrition of leucoselect phytosome (LP), standardized expression of MiR106B mRNA and MiR-106b in GSE expression of athymic mice, and increased expression of CDKN1A mRNA in tumor xenografts correlated with a significant reduction in tumor growth." (PMID 33202575, 2020). "CDKN1A mRNA and protein expression levels were of prognostic relevance independent from tumor stage." (PMID 32079343, 2020). "In this study, we found that the oncolytic effect of M1 virus negatively correlated with the expression of CDKN1A in tumor cells." (PMID 33037696, 2020). "Several IHC studies imply that nuclear expression of CDKN1A indicates its tumor-suppressive role, while its presence in the cytoplasm favors an oncogenic role." (PMID 32079343, 2020). "The knockdown of CDKN1A enhances the oncolytic effect of M1 virus in nude mice bearing human tumor cells, which largely represents the characteristics of human cancer." (PMID 33037696, 2020). "Previous studies emphasize CDKN1A’s important tumor suppressive role by showing that its depletion in cell line models leads to DNA damage and chromosomal instability but also permits carcinogenesis from chronically damaged kidney epithelial cells." (PMID 32079343, 2020). "We show that loss of STRIP1 induces the expression of cyclin dependent kinase inhibitors (CKI) including CDKN1A (p21), which leads to cell cycle arrest and reduced tumor growth." (PMID 32258031, 2020).
tumor (continued). "There was increased expression of pro-proliferative and tumor promoting genes such as Ccnb1, Ccnd1, Survivin, and Myc, while the expression of Cdkn1a, an inhibitor of cell cycle progression, was significantly reduced in Nlrp12-/- HCC." (PMID 30990169, 2019). "Kaiso causes transcriptional repression of several well-known tumor suppressor genes like Retinoblastoma (Rb), Hypermethylated In Cancer 1 (HIC1) and Cyclin-Dependent Kinase Inhibitor 1A (CDKN1A)." (PMID 31245293, 2019). "The primary tumor sample with the D850V mutation in PDGFRB had concurrent mutations in PTCH1 (c.961C > A), ATR (c.4704C > G), and CDKN1A (c.419_420delGA)." (PMID 31480474, 2019). "The tumor suppressor activity is related to induction of cell cycle arrest via transcriptional upregulation of the CDKN1A gene, which encodes p21Cip1." (PMID 30933982, 2019). "ARID1A, as a tumor suppressor, regulates CDKN1A and SMAD3 transcription and tumor growth by collaborating with p5344." (PMID 31772679, 2019). "FOXOs’ anti-tumour function has been related to the regulation of key genes participating in cell death and cell cycle arrest, such as p27KIP1, CDKN1A/p21, FasL, Trail and Bim." (PMID 30621735, 2019). "miR-106b is reported to promote the tumor growth through targeting tumor suppressor genes, such as Pten, Cdkn1a, E2F1, Setd2, Runx3, Smad7, Cdkn1a, and Bim." (PMID 31547867, 2019). "The tumor suppressor gene CDKN1A was one of the most upregulated while oncogenic cell cycle genes such as WDHD1 and BIRC5 were among the downregulated genes." (PMID 30543688, 2018). "Oral gavage of leucoselect phytosome (LP), a standardized GSE to athymic nude mice down-regulated MIR106B mRNA and miR-106b expressions, and increased CDKN1A mRNA expression in tumor xenografts, correlating to significant reduction of tumor growth." (PMID 29643994, 2018). "As discovered by our findings, SNHG1is capable of binding to EZH2, which is a kind of histone methylation modification complex in the nucleus, thus suppressing the target gene’s expression, which includes CDKN1A, an innovative tumor suppressor in CCA." (PMID 29970899, 2018). "CDKN1A (cyclin-dependent kinase inhibitor 1A; also known as p21, Cip1, Waf1) is a tumor suppressor that regulates cell proliferation and binds to and inhibits kinase activity of Cdk2 and Cdk1, leading to cell cycle arrest." (PMID 30514244, 2018). "Herein, we demonstrate the positive combinatorial effect ascorbate has upon the demethylating agents AZA and DAC, resulting in higher 5-hmdC-levels and increased expression of the tumour suppressor levels of CDKN1A." (PMID 30214687, 2018). "In our previous study, we showed that simultaneous inhibition of CDKN1A and telomerase by imetelstat leads to synergistic tumor growth inhibition." (PMID 29986697, 2018). "A mass of studies have demonstrated that PPARγ agonists via inhibiting the expression of cyclinD1, cyclinB, cyclinE, CDK4 and CDK2 and increasing the expression of CDKN1A to prevent cell cycle from G1 to S phase to prohibit tumor cells proliferation." (PMID 29642873, 2018). "In a more general sense, it has been suggested that the subcellular localization of CDKN1A defines its function as a tumor suppressor (nuclear localization) or oncoprotein (cytoplasmic localization)." (PMID 28231799, 2017). "The present analysis showed, for the first time, that the anti-tumor effect of fisetin was mediated mainly through activation of CDKN1A, SEMA3E, GADD45B and GADD45A and down-regulation of TOP2A, KIF20A, CCNB2 and CCNB1 genes." (PMID 28052097, 2017).
tumor (continued). "The proteins encoded by CDKN1A and CDKN2A can inhibit the activity of cyclin-CDK and function as tumor suppressors to control cell cycle in HBV-related HCC." (PMID 29191172, 2017). "By contrast, exogenous expression of human ERRβ has tumor suppressive activities that activate the G1/S checkpoint through the induction of CDKN1A (p21) in prostate cancer cells." (PMID 27363015, 2016). "Consistently, we have illustrated that MycN knockdown in human NCSCs increased the expression of Cdkn1a, Cdkn2a and Cdkn2b, emphasizing the critical role of these tumor suppressors in stem cell growth and cell cycle progression." (PMID 26815535, 2016). "Immunohistochemical (IHC) staining of xenograft sections revealed increased expression of the cyclin-dependent kinase inhibitor CDKN1A (p21CIP1) in tumours generated by TGFβ knockdown cells." (PMID 27835901, 2016). "RACGAP1 in the tumor was also associated with CTNBB1 expression, and inversely associated with CDKN1A gene expression." (PMID 26778597, 2016). "Cells with reduced ATG12 expression produced significantly more colonies in soft agar than control cells, similar to CDKN1A knockdown, consistent with a role of autophagy in tumor suppression." (PMID 26956429, 2016). "While the canonical Myc target genes we examined were slightly elevated in KPH2 tumours (or decreased in the case of Cdkn1a), Ano1 expression was significantly increased, suggesting other input(s) are likely influencing its transcription." (PMID 26837714, 2016). "miR-22 acts as a tumor suppressor and induces cellular senescence by regulating cyclin-dependent kinase inhibitor 1A (CDKN1A), cyclin-dependent kinase 6 (CDK6), sirtuin 1 (SIRT1), and specificity protein 1 (Sp1)." (PMID 26927063, 2016). "The cooperative effect of CDKN1A and TGM2 knockdown indicates that they provide complementary contributions to tumor suppression and that loss of each gene function is critical for oncogenic transformation." (PMID 26956429, 2016). "Their RNASeq data indicated that MSI‐2 acts as a pleiotropic inhibitor of known intestinal tumor suppressors, including Lrig1, Bmpr1a, Cdkn1a, and Pten." (PMID 26775684, 2016). "Our results showed that after 1 week of MycN knockdown, there was significant increase in the expression of well-recognized tumor suppressors that induce G1 cell cycle arrest, such as Cdkn1a, Cdkn2a and Cdkn2b." (PMID 26815535, 2016). "As a major player in mammalian cell cycle progression, CDKN1A inhibits cyclin/cdk2 complexes and plays a crucial role in mediating growth arrest when cells are exposed to DNA damaging agents, implying its tumor suppressive role." (PMID 26582573, 2015). "In the present study, RTA 408 reduced cyclin D1 and increased CDKN1A protein levels in all eight tumor lines." (PMID 25897966, 2015). "In order to determine the expression of miR-190a, AR, YB-1, CDKN1A, and Ki-67 in tumor tissues, we conducted RT-PCR and IHC staining on tumor samples." (PMID 26314494, 2015).
tumor (continued). "The suppressor of cytokine signaling 1 (SOCS1) and cyclin-dependent kinase inhibitor 1A (p21KIP) are known to regulate tumor cell proliferation." (PMID 25893382, 2015). "Two additional tumor suppressors, CDKN1A (p21) and CDKN2A (p16), were shown to be direct targets of miR-10b, a miRNA significantly upregulated in malignant gliomas." (PMID 26287251, 2015). "And we know, TGF-β/Smad3 signaling has been regarded as tumor suppressor during tumor progression since TGF-β-induced CDKN1A (P16) and CDKN2B (P15) expression is correlated with tumor inhibition." (PMID 24427302, 2014). "Selective ablation of tNasp via RNAi has previously been demonstrated to induce apoptosis in tumor cells via expressional upregulation of the cyclin dependent kinase inhibitor 1a (Cdkn1a/p21, ENSMUSG00000023067)." (PMID 24586484, 2014). "The miR-17/92 cluster is highly involved in controlling tumor growth via regulation of proliferation and apoptosis and another cell cycle regulator, cyclin-dependent kinase inhibitor 1A (p21), is also targeted by miR-17." (PMID 23739951, 2013). "Tumor cell proliferation was inhibited by the increased expression of cyclin-dependent kinase inhibitor 1 (p21/WAF1; Cdkn1A), and the apoptosis was induced by the activated expression of the Bcl-2–associated X protein (BAX)." (PMID 23840792, 2013). "Tumour-suppressor genes like CDKN1A are often repressed in cancer tissues and remain in a repressed state during successive stages of cell proliferation." (PMID 23658227, 2013). "Tumor cell proliferation was inhibited by increased expression of cyclin-dependent kinase inhibitor 1 (p21waf1/cip1; Cdkn1A), and apoptosis was activated by elevated expression of pro-apoptotic BCL-Associated X (Bax)." (PMID 23840792, 2013). "Hypermethylation within the promoter strongly correlated with decreased CDKN1A mRNA expression in tumour cells and such patients showed poor prognoses." (PMID 23658227, 2013).
tumor (continued). "To test the impact of p21cip1 genetically, we monitored tumor development in a cohort of Miz1ΔPOZ;cdkn1a−/− mice." (PMID 22509363, 2012). "p21Cip1/Waf1, also known as Cyclin-dependent kinase inhibitor 1A (CDKN1A) acts as a master effector molecule of multiple tumor suppressor pathways." (PMID 21949731, 2011). "Further supporting its importance in neoplasia, the double mutant mouse, Apc1638N+/− Cdkn1a−/−, exhibits a synergistic increase in its tumor burden." (PMID 20824133, 2010). "We have previously used xenograft studies to show abrogation of a single gene, CDKN1A (p21), increases xenograft tumor radiosensitivity to large fractions (15 Gy) in vivo but does not alter cellular radiosensitivity in vitro." (PMID 20704711, 2010). "The double mutant Apc1638N+/− Cdkn1a−/− mouse was previously shown to exhibit a synergistic increase in its tumor burden when compared with the single mutants." (PMID 20824133, 2010). "We first compared CDKN1A protein expression among the three types of tumor, considering the intensity of the bands obtained through the Western Blotting technique." (PMID 20169278, 2009). "The relationships between CDKN1A expression levels and the prognostic factors in other types of tumor are similarly contradictory." (PMID 20169278, 2009). "To validate our experimental conditions we next measured in Akata cells the expression of cellular genes known to be reactivated by Zebularine in other tumor cell lines including CDKN1A, CDKN1B and CDKN2A genes." (PMID 17214905, 2007). "CDKN1A also exhibits tumor suppressor activity in other hematological malignancies." (PMID 41040512, 2025). "Indeed, numerous studies have highlighted the tumor-suppressive role of CDKN1A in various types of cancers." (PMID 41345520, 2025). "Whereas a strong toxicity and compensation profile could be expected for the tumor suppressor and cell cycle regulator CDKN1A, the effects of RBM14 overexpression on cancer cell growth are novel." (PMID 39870664, 2025). "Knockdown of COX6A1 significantly upregulated senescence-associated genes, such as CDKN1A and CDKN2A, indicating that COX6A1 may inhibit tumor progression by inducing senescence." (PMID 40331946, 2025). "By co-activating metabolic deprivation (via SREBF2 inhibition), loss of invasive potential (via TGF-β suppression), and stress/CTL-induced apoptosis (via HSPA1/CDKN1A), these agents generate a lethal epigenetic storm that suppresses tumor growth, metastasis, and therapy resistance." (PMID 41283357, 2025). "Meanwhile, Cdkn1a and Mif were the most upregulated genes involved in the regulation of cell population proliferation in shNKX2‐1 tumor‐infiltrated neutrophils when compared to the shCtrl tumor‐infiltrated neutrophils." (PMID 39113226, 2024).